Y_RNA (Y RNA )
Gene: Miscellaneous RNA gene on chromosome 14 (63,848,261 to 63,848,362, reverse strand). Ensembl gene ENSG00000202182.
Homologues: Orthologues: chimpanzee Y_RNA (99% identical), macaque Y_RNA (97% identical). Paralogues in human: RNY3 (94% identical), Y_RNA (94% identical), RNY3P1 (93% identical), Y_RNA (93% identical), Y_RNA (92% identical), Y_RNA (91% identical), Y_RNA (90% identical), Y_RNA (89% identical), RNY3P11 (88% identical), RNY3P16 (88% identical), Y_RNA (88% identical), RNY3P14 (87% identical), and 100 more.